IL5 (interleukin 5)
Diseases named in the same sentence as IL5 in open-access papers (continued):
Sharing a sentence is not in itself a finding about the gene and the disease.
allergic asthma (continued). "Th2 type cytokines such as IL-4, IL-5 and chemokines have been implicated in the pathology of allergic asthma." (PMID 19657391, 2009). "Allergic asthma is often associated with activation of IL-5 gene cluster, a pattern compatible with predominant activation of Th2-like T-lymphocyte population." (PMID 16164761, 2005). "Recent studies described a specific subpopulation of Th2 cells, called pathogenic T helper 2 cells (Tpath2 cells), which are capable of causing allergic asthma and chronic allergic dermatitis by producing excessive amounts of type-2 cytokines, particularly IL-5 and IL-1327–29." (PMID 37337050, 2023). "Additionally, IL-5 and IL-17 production by T-cells from allergic asthma patients are reported to be positively associated with the severity of major depressive disorders." (PMID 36045388, 2022). "In humans, an allergic asthma response is often associated with a systemic increase of IL-4 and IL-5, both of which have been linked to an increased likelihood of birthing a child later diagnosed with neurodevelopmental disorders when higher levels occur during pregnancy." (PMID 36009104, 2022). "Although there are different disease phenotypes, the hallmark of allergic asthma is a type 2 immune response, characterized by IL-4, IL-5, and IL-13 secretion by T helper 2 (Th2) lymphocytes, IgE secretion, recruitment and activation of eosinophils, mast cells, dendritic cells and epithelial cells." (PMID 34834178, 2021). "In allergic asthma, Cloots and coworkers showed that mice genetically deficient for Arg1 displayed a reduction in Il4, Il5, Il13, Ccl2, and Ccl11, all Th2-related genes, suggesting that Arg1 may regulate type 2 inflammation." (PMID 34834178, 2021). "Our study suggests that Sema3E could be considered as a novel treatment for chronic allergic asthma via regulation of both Th2, e.g. IL-4 and IL-5, and Th17, e.g. IL-17A, associated cytokines." (PMID 29228740, 2017). "The results showed that the expression levels of TSLP, IL-33, IL-4, IL-5, and IL-13 were higher in clusterB or gene clusterB than those in clusterA or gene clusterA, which suggested that clusterB or gene clusterB is highly linked to allergic asthma characterized by the Th2 immune response." (PMID 33763115, 2021). "Similarly, IL‐5 is a critical eosinophil survival associated with allergic asthma." (PMID 27621809, 2016). "Specifically, SCFAs enhance regulatory T cell development, suppress allergic inflammation, and reduce Th2-type cytokine production, including IL-4, IL-5, and IL-13, in allergic asthma." (PMID 40529126, 2025). "JAK kinases bind to βc at Lys457, Lys461, and Lys467, promoting βc's subcellular localization, IL-5-induced endocytosis, turnover, and signaling, thereby influencing eosinophil function in allergic asthma." (PMID 40893770, 2025). "IL-5 remained elevated in allergic asthma cases despite treatment, indicating persistent eosinophilic activity." (PMID 40364125, 2025). "Eosinophils have long been associated with allergen-induced airway responses, yet anti-IL-5/IL-5R agents are not effective in blocking responses to allergens, calling into question the role of eosinophils (and anti-IL-5) in early-onset, allergic asthma." (PMID 39586024, 2025). "Allergic asthma, which is common in childhood, exhibits a T2-high response with activation of IL-4, IL-5, IL-9, or IL-13, accompanied by eosinophilic inflammation." (PMID 40867700, 2025). "Allergic asthma is typically characterized by high expression of IL-4, IL-5, and IL-13, along with elevated IgE levels and eosinophil infiltration; it is a prototypical type 2 inflammation-driven disease." (PMID 40430465, 2025). "The immune response to allergic asthma is primarily regulated by Th2 lymphocytes, which release IL-4, IL-5, and IL-13." (PMID 39858200, 2025). "This influx of ILC2 cells combined with the production of IL‐4, IL‐5 and IL‐13 from these Th2‐like Tregs worsens allergic asthma and food allergy." (PMID 40497455, 2025).
allergic asthma (continued). "Bronchoalveolar lavage fluid from patients with allergic asthma (AAS) exhibits elevated levels of Th2 cytokines, particularly IL-5, which is strongly linked to eosinophilic inflammation." (PMID 40529241, 2025). "Th2 cells in allergic asthma produce IL-4, IL-5, and IL-13, driving B cell differentiation, antibody production, eosinophil increase, and airway inflammation." (PMID 40893770, 2025). "For instance, they recommended anti-IgE therapy for allergic asthma, anti-IL-5 for eosinophilic asthma, and dupilumab as an option for eosinophilic or allergic asthma with frequent exacerbations, especially when maximal therapy has been reached." (PMID 40843371, 2025). "α-Asarone inhibited the phosphorylation level of STAT3, thus inhibiting mast cell activation, inflammatory cell infiltration, and the release of IL-5 and IL-13 in lung tissue, and finally effectively alleviating allergic asthma." (PMID 39444792, 2024). "Another major feature of the airway inflammation induced in allergic asthma is a type 2 immune response that involves the release of various cytokines, including IL-4, IL-5, and IL-13." (PMID 38790633, 2024). "Safranal, the main constituent of C. sativus, attenuates AHR and airway structural changes during allergic asthma and decreases IL-13 and IL-5 and other inflammatory cytokines in mouse lungs." (PMID 39263346, 2024). "It has been shown that Th2 cytokines of IL-13, Il-4, and IL-5 are deeply involved in the early phase of allergic asthma pathogenesis." (PMID 39062810, 2024). "First, Th2 cells produce IL-4, IL-5, and IL-13, which promote allergic asthma, and higher Se intake skews differentiation toward Th1/Treg and away from Th2 phenotypes." (PMID 38826577, 2024). "Another controlled study found that aqueous extract of aniseed significantly reduced the gene expression of IL-5 and IL-13 and the protein levels of inflammatory cytokines in the lung tissue of laboratory mice with allergic asthma treated." (PMID 38292939, 2024). "CCR4 is expressed by type‐2 inflammatory cells, including Th2 cells and innate lymphoid cells, which generate IL‐4, IL‐5, and IL‐13, and contribute to the etiology of allergic asthma." (PMID 39508721, 2024). "HDM is known to trigger the release of allergic asthma related cytokines, namely IL-4, IL-5 and IL-13 from Th2 cells, innate immune cells and innate lymphoid cells thereby driving eosinophil-predominant airway inflammation." (PMID 39129025, 2024). "Results from our study support the possible role of Nr1d1/2 (reduced mRNA expression) in chronic HDM-induced allergic asthma with heightened il4, il5, and il13 expression at ZT12." (PMID 37664635, 2023). "In experiments in vitro, the percentage of ILC2s in peripheral blood from patients with allergic asthma was significantly greater and responsive to IL-33 and IL-25, leading to the production of higher levels of IL-5 and IL-13 than healthy controls." (PMID 36674744, 2023). "In a recent study, CD66bhighCD15high eosinophil levels correlated with blood eosinophil number and IL-5 levels in sputum in allergic asthma with airway eosinophilia." (PMID 37371101, 2023). "In a mouse model of experimental allergic asthma, local application of recombinant IL-37 lowered the secretion of IL-4, IL-5, and IL-13, thereby reducing Th2-mediated allergic airway inflammation." (PMID 38067193, 2023). "In this research, our emphasis was on Th2 cell differentiation, giventhe importance of this subset in allergic asthma due to the secretionof IL-4, IL-5, and IL-13." (PMID 38144091, 2023). "Allergic asthma is a respiratory disease initiated by type-2 immune responses characterized by secretion of alarmins, interleukin-4 (IL-4), IL-5, and IL-13, eosinophilic inflammation, and airway hyperresponsiveness (AHR)." (PMID 36865540, 2023). "Six of the hub genes were markedly elevated in murine asthmatic lungs and were positively associated with IL-5, IL-13 and MUC5AC, which are the key mediators of allergic asthma." (PMID 36211429, 2022).
allergic asthma (continued). "integerrima reportedly subdued the expressions of inflammatory molecules, TNF-α, IL-4, and IL-5 in the mouse model of ovalbumin (OVA) induced allergic asthma, thereby alleviating pulmonary edema." (PMID 36386162, 2022). "Here, we showed that our model of MAA recapitulates the exposure to cytokines that are hallmarks of the allergic asthma response, including increased levels of IL-4, IL-6, IL-5, IL-13, and IL-17." (PMID 36009104, 2022). "Imuno TF influenced cellular signaling associated to allergic asthma once downregulated STAT6 expression as well as decreased IL-4, IL-5, and IL-13 in lung and serum." (PMID 36685604, 2022). "MX1, RSAD2, IFIT1, IFI27, OAS3, and SAMD9L were markedly elevated in HDM-treated mice and positively associated with IL-5, IL-13 and MUC5AC (key mediators of allergic asthma)." (PMID 36211429, 2022). "Th2 cells secreting IL–4, IL–5, and IL–13 play a key role in the inflammatory process in allergic asthma, smooth muscle spasms, and mucus production." (PMID 36558973, 2022). "IL-4 and IL-5 along with other Th2-cytokines are involved in the airway inflammation observed in the lungs of patients with allergic asthma." (PMID 35547729, 2022). "Th2 cells contribute to the pathogenesis of allergic asthma by producing Th2 cytokines, such as IL-4, IL-5, and IL-13, leading to eosinophil accumulation in the airway wall, mucus overproduction, and IgE synthesis." (PMID 36077141, 2022). "Th2 cytokines, including IL‐4, IL‐5, and IL‐13, are important factors in the pathophysiological characteristics of allergic asthma." (PMID 35344278, 2022). "The E1 subset (CD66b-high and CD15-high) predominates in patients with allergic asthma and eosinophilic inflammation and is correlated with blood eosinophils, FeNO, and IL-5 in sputum supernatant." (PMID 36293979, 2022). "Specifically, IFN-G, IL-13, IL-5, and IL-4R showed an especially high overall relationship with allergic conditions (respiratory allergy and allergic asthma)." (PMID 33936056, 2021). "Cytokines released from Th2 cells like IL-5 and IL-4 stimulate IgE secretion from the B cells that play an important role in allergic asthma." (PMID 35046828, 2021). "OXY significantly ameliorates allergic asthma by suppressing T-cell response including down regulation of IL-4, IL-5, and IL-13 expression levels." (PMID 33946346, 2021). "Individuals with allergic asthma have eosinophilic inflammation in the lungs, as well as increased mediators related to the adaptive response of the Th2 subset, such as IL-4, IL-5 and IL-13, and serum IgE elevation." (PMID 34557509, 2021). "Evidence states that IL-4, IL-5, and IL-13 drive allergic asthma, which explains the importance of these molecules as drug targets in the management of T2 high allergic asthma." (PMID 34572281, 2021). "The activated T lymphocytes then produce several pro-inflammatory cytokines such as interleukin (IL) IL-4, IL-5, IL-9, IL-13, and GM-CSF that are major components of the inflammatory response in AR as well as allergic asthma." (PMID 34638811, 2021). "Kaempferol, one of the principal constituents in S. nigra, has its therapeutic implications in the treatment of allergic asthma by inhibiting IL-4, IL-5, and IL-13 secretion." (PMID 32617136, 2020). "Th2-type cytokines such as IL-4, IL-5, and IL-13 play a vital role in the progression of the allergic asthma." (PMID 32617136, 2020). "Th2 type cytokines (e.g. interleukin (IL)-4, IL-5, and IL-13) play a major role in the pathogenesis of allergic asthma." (PMID 32600285, 2020). "For instance, targeting IL-5 with mepolizumab on benralizumab is relevant for the eosinophilic phenotype whereas omalizumab concerns allergic asthma." (PMID 31996218, 2020). "The Th2 cytokines that play an important role in allergic asthma, like IL-5, IL-13, CCL17, and IL-33 along with total IgE in serum were measured." (PMID 32582180, 2020).
allergic asthma (continued). "Similar to the case in the mRNA expression level of IL-5 and IL-13 in allergic asthma, the percentages of IL-5+ and IL-13+ CD4+ Th cells were significantly lower in HDM-sensitized Tlr9−/− mice than in HDM-sensitized WT mice." (PMID 33093516, 2020). "The polarization of immune responses towards Th2 cells that it has destructive effects on lung with the secretion of IL-4 and IL-5 cytokines indicating activation of this pathway during allergic asthma." (PMID 31143692, 2019). "Like Th2 cells, ILC2s secrete IL-5 and IL-13 and participate in processes such as antihelminth infection, tissue repair after influenza virus infection, and allergic asthma." (PMID 31320835, 2019). "In a mouse model of ovalbumin-induced allergic asthma, oral administration of OR in doses of 0.05 and 0.5 g/kg BW for 8 weeks remarkably decreased inflammatory cell count as well as contents of IL-4, IL-5, and IFN-γ in BALF." (PMID 31281578, 2019). "Bronchial inflammation, smooth muscle spasm, and mucus production in allergic asthma are triggered by IL-4, IL-5, and IL-13, which are released by Th2 cells." (PMID 31637021, 2019). "Controlling Th2-mediated responses (i.e., the production of IL-4, IL-5, and IL-13) can have a potential therapeutic role in allergic asthma." (PMID 31637021, 2019). "In allergic asthma, the importance of Th2 cytokines, especially IL-5, in the induction of allergic pulmonary inflammation and airway hyperreactivity has been reported." (PMID 31001262, 2019). "Following induction of allergic asthma and administration of aqueous extract of P. atlantica gum, Th2 (IL-5 and IL-4) and Th17 cytokines (IL-17) significantly decreased, which did not vary significantly among different doses of the extract." (PMID 31143692, 2019). "Results revealed that thymol effectively reduced the symptoms of allergic asthma through dose-dependent inhibition of IL-4, IL-5 and IL-13 production at 4, 8 and 16 mg/kg in OVA-challenged mice." (PMID 31275149, 2019). "Cytokines such as IL-4, IL-5, and IL-13 have a close relation with the phenotype of allergic asthma." (PMID 30783201, 2019). "This suggests that widely used concentrations of MPA can have a positive influence on the health status of patients with allergic and non-allergic asthma by decreasing IL-5 production by T cells, thus reducing eosinophilic infiltration of the lungs." (PMID 31001262, 2019). "Intragastric administration of 1-MID in doses of 40 and 80 mg/kg BW to a rat model of ovalbumin-induced allergic asthma for 7 days significantly decreased contents of IL-5 and eotaxin as well as eosinophil count in BALF." (PMID 31281578, 2019). "The type 2 cytokines, interleukin- (IL-) 4, IL-5, IL-9, and IL-13, are the major drivers of allergic asthma and studies." (PMID 31737687, 2019). "IL-5 generated from Th2 cells attracts and activates eosinophils, leading to tissue destruction in allergic asthma." (PMID 31889961, 2019). "Th2 cells then mediate the allergic asthma pathway through proinflammatory cytokines—i.e., interleukins (IL)-4, IL-5, IL-9, and IL-13—leading to the production of immunoglobulin E (IgE) early in the cascade and, later, eosinophils." (PMID 29176991, 2017). "Its production is stimulated early in the allergic asthma cascade by the release of IL-4, IL-5, and IL-13 through activated Th2 cells." (PMID 29176991, 2017). "Decreased numbers of eosinophils in anti-IL-5-treated mice were protective in an OVA-model of allergic asthma (references in Walsh et. al.)." (PMID 27442134, 2016). "In the allergic asthma model, the Th2 cytokines, such as IL-4, IL-5, and IL-13, were clearly increased in the lung tissues." (PMID 27669297, 2016). "At 7 h and 24 h after bronchial challenge, the induced sputum IL-5 levels increased significantly in the patients with allergic asthma and those with allergic rhinitis compared with the healthy subjects." (PMID 25829869, 2015).
allergic asthma (continued). "We found elevated serum IL-5 levels, especially 24 h after bronchial challenge, in the patients with allergic asthma compared with the baseline values and other groups." (PMID 25829869, 2015). "There was a significant increase in the induced sputum IL-5 levels in the patients with allergic asthma and those with allergic rhinitis compared with the healthy subjects at 24 h before bronchial challenge." (PMID 25829869, 2015). "IL-5, a Th2 cytokine, acts on eosinophils, basophils, mast cells, and B cells and elevated levels were found in allergy asthma and hypereosinophilic syndrome." (PMID 26236424, 2015). "Allergic asthma is primarily mediated by Th2 cells, which secrete the characteristic cytokines IL-4, IL-5, and IL-13." (PMID 24955743, 2014). "Th2 cytokines including IL-4, IL-5, and IL-13 have been shown to play crucial roles in the regulation of pulmonary inflammatory responses in allergic asthma." (PMID 25415454, 2014). "Taken together, our results demonstrate possible therapeutic potentials of sesamin in reducing the TH2 immune reaction sand the following inflammatory response mediated by IL-4, IL-5, and IL-13 in human allergic asthma." (PMID 24755955, 2014). "Th2 cells are critical for the induction of allergic asthma via production of IL-4, IL-5, IL-13, and eotaxin." (PMID 24658532, 2014). "It is well known that overexpression of GATA-3 predisposes for Th2-mediated diseases such as allergic asthma and suppression of GATA-3 expression in the lung reduces IL-4, IL-5, and IL-13 productions concurrently." (PMID 23800145, 2013). "It was reported that eosinophils, Th2 lymphocytes and their released inflammatory mediators, such as IL-5 and IL-13, played a crucial role in human allergic asthma." (PMID 23731974, 2013). "IL-5 plays an important role in the progression of the eosinophilic inflammatory response in allergic asthma." (PMID 24204674, 2013). "T helper 2 (Th2) cytokines, including IL-4, IL-5 and IL-13, predominate primarily in mild to moderate allergic asthma." (PMID 24204835, 2013). "Th2 cell, a sub-group of lymphocytes, plays an important role in the initiation and progression of allergic asthma by releasing of IL-4 and IL-5 cytokines." (PMID 23837463, 2013). "IL-5 in allergic asthma pathogenesis primarily comes from Th2 lymphocytes and tissue-infiltrated eosinophils." (PMID 23855490, 2013). "The inflammatory process in allergic asthma is dominated by Th2 cells that produce IL-4, IL-5, and IL-13, which activate eosinophils and induce the production of IgE by B cells." (PMID 22439901, 2012). "While IL-4 and IL-5 are known to be upregulated in allergic asthma, IFN-γ is generally thought to be downregulated." (PMID 21810230, 2011). "Interestingly, IL-5 levels were consistently elevated in BT patients with allergic asthma (AA), suggesting persistent eosinophilic inflammation despite biological therapy, more likely unaffected by TNF-α or IL-17 blockade." (PMID 40364125, 2025). "IFN-γ is known to reduce the levels of IL-5, which are associated with airway inflammation and hyperreactivity in allergic asthma, but this effect is not reflected in our results, probably due to dynamic interplay among TH1 and Th2 immune responses." (PMID 40872499, 2025). "Allergic asthma is generally classified as an eosinophilic airway disorder, and previous studies have focused on the role of Th2 cells and type 2 cytokines, including IL-4, IL-5, and IL-13." (PMID 38790633, 2024). "In recent years, several biologic antibodies have been clinically introduced such as omalizumab (anti-IgE), dupilumab (anti-IL-4), and mepolizumab (anti-IL-5), because IgE and Th2 cytokines (IL-4, IL-5, and IL-13) play crucial roles in allergic asthma pathogenesis." (PMID 39062810, 2024).